NDRG2 (NDRG family member 2)
Diseases named in the same sentence as NDRG2 in open-access papers (continued):
Sharing a sentence is not in itself a finding about the gene and the disease.
thyroid cancer (5 papers, 2008 to 2020). "Whether the down-regulation of NDRG2 in thyroid carcinoma is a cause or a consequence remains presently unclear." (PMID 18940011, 2008). "Expression of Ndrg2 was reduced in thyroid cancers, compared to normal tissues, consistent with the microarray analysis." (PMID 18940011, 2008). "Our results showed significantly reduced expression of Ndrg2 in thyroid cancers, indicating the potential involvement of NDRG2 in the processes of thyroid carcinoma formation." (PMID 18940011, 2008). "Further studies are needed to investigate how NDRG2 is involved in the progression from normal thyroid tissue to thyroid cancer." (PMID 18940011, 2008). "The data showed that expression of NDRG2 mRNA in thyroid cancer tissues was lower than in the adjacent cancer group." (PMID 18940011, 2008). "In accord with our previous finding that Myc can transcriptionally repress human NDRG2, we also detected amplification of c-Myc in thyroid cancers, consistent with findings in other cancers." (PMID 18940011, 2008). "To examine Ndrg2 at the levels of mRNA and protein, we analyzed a collection of clinical samples, including 35 thyroid cancers and 40 adenomas." (PMID 18940011, 2008). "Based on the detection of Ndrg2 protein expression in thyroid cancer tissues, real-time RT-PCR was used to investigate NDRG2 mRNA levels in thyroid adenomas and carcinomas." (PMID 18940011, 2008). "Our data provide novel insight into the important role of NDRG2 in the development of thyroid cancers." (PMID 18940011, 2008). "In conclusion, the protein and mRNA expression levels of NDRG2 were significantly decreased in thyroid cancers with c-Myc amplification." (PMID 18940011, 2008). "In the present study, we demonstrated that the mRNA and protein expression levels of NDRG2 were decreased in thyroid cancers, compared to normal tissues." (PMID 18940011, 2008). "Upon examining these levels of expression, we noted a tendency towards decreased NDRG2 expression with increasing c-Myc expression in thyroid cancer." (PMID 18940011, 2008). "Using real-time PCR and western blot analysis, we assessed the mRNA and protein expression levels of NDRG2 in thyroid carcinomas and adenomas." (PMID 18940011, 2008). "With immunostaining analysis, a different expression pattern of Ndrg2 was detected in thyroid carcinomas and normal tissues." (PMID 18940011, 2008). "When comparing adenomas or carcinomas with adjacent normal tissue from the same individual, the mRNA expression level of NDRG2 was significantly decreased in thyroid carcinoma tissues, while there was little difference in adenoma tissues." (PMID 18940011, 2008). "However, analysing both colon and thyroid cancer in a more quantitative manner and using larger sample sets, we and others have demonstrated a clear and significant decrease in NDRG2 mRNA levels in both cancer types." (PMID 21226903, 2011). "As human NDRG2 is important in cell proliferation and differentiation, we investigated whether NDRG2 participated in the carcinogenesis of thyroid cancer." (PMID 18940011, 2008). "Finally, potential correlations between NDRG2 mRNA expression, the different histotypes of thyroid cancers and distant metastases were investigated." (PMID 18940011, 2008). "The immunostaining analysis revealed a decrease of Ndrg2 expression in thyroid carcinomas." (PMID 18940011, 2008). "As we did not define the role of Ndrg2 in the metastasis of thyroid cancer, the mechanism of the involvement of Ndrg2 in cancer needs to be more thoroughly examined in future studies." (PMID 18940011, 2008). "There was a negative correlation between Myc and NDRG2 expression levels in the thyroid carcinomas (r = -0.336, p = 0.048)." (PMID 18940011, 2008).
adenoma (4 papers, 2007 to 2017). A neoplasm arising from the epithelium. "In order to determine the stage at which NDRG2 expression is down-regulated in the adenoma-carcinoma sequence we also examined normal and affected tissue from low- and high-risk adenomas." (PMID 17935612, 2007). "Upon examination of the mean values in affected tissue (low- and high-risk adenomas and carcinoma), a trend towards a decreased NDRG2 expression with increasing tumor grade was observed (p < 0.001)." (PMID 17935612, 2007). "However, a comparison of normal and high-risk adenoma from the same individual showed a highly statistically significant reduction (p < 0.001) in NDRG2 level." (PMID 17935612, 2007). "In human thyroid tissue, we also detected predominantly cytoplasmic localization of Ndrg2 in both normal and adenoma tissues." (PMID 18940011, 2008). "The results showed that NDRG2 expression was significantly decreased in carcinomas, but was only slightly reduced in adenomas." (PMID 18940011, 2008). "Our results suggest that down-regulation of NDRG2 expression occurs during the progression from adenoma to carcinoma." (PMID 17935612, 2007). "The MS-PCR was used for NDRG2 promoter methylation analysis and gene mRNA expression levels were evaluated by qRT-PCR in 68 non-functioning and 73 functioning adenomas." (PMID 28390436, 2017).
clear cell renal cell carcinoma (4 papers, 2010 to 2015). "Recently, the anti-tumor activity of N-myc downstream-regulated gene 2 (NDRG2) was shown decreased expression in clear cell renal cell carcinoma (CCRCC), but the role of the down-expression of NDRG2 has not been described." (PMID 20673333, 2010).
ischemia (4 papers, 2013 to 2022). A hypoperfusion of the BLOOD through an organ or tissue caused by a PATHOLOGIC CONSTRICTION or obstruction of its BLOOD VESSELS, or an absence of BLOOD CIRCULATION. "We first examined whether NDRG2 is associated with the changed neurological outcomes in ischemia following a timeline." (PMID 31250377, 2020). "The deletion of NDRG2 or treatment with the Na+/K+-ATPase β1 peptide significantly increased neuronal death upon a glutamate challenge and aggravated brain damage after ischemia." (PMID 31250377, 2020). "NDRG2 was reported as an early-stage stress response gene, and its expression is upregulated under excitotoxic conditions in the brain, including ischemia, hemorrhage, trauma, and Alzheimer’s disease." (PMID 31250377, 2020). "NDRG2 is phosphorylated in response to insulin stimulation and has been identified as a mediator of the cardioprotective effects of insulin on ischemia-reperfusion injuries following myocardial infarctions." (PMID 27657503, 2016). "We conclude that the lactate/NDRG2/TNFα signaling axis may provide an extended mechanistic clue and a valuable approach for modulating neuroinflammation during the early stages of ischemia." (PMID 36572898, 2022). "The NDRG2-mediated astroglial glutamate uptake from the cerebral interstitial fluid is essential for protecting the brain from glutamate excitotoxicity following ischemia." (PMID 31250377, 2020). "The phenomenon of NDRG2 signals co-localized with TUNEL-positive cells in ischemic penumbra suggested that NDRG2 might be involved in cellular apoptosis induced by ischemia." (PMID 23451161, 2013).
lung adenocarcinoma (4 papers, 2014 to 2025). A carcinoma that arises from the lung and is characterized by the presence of malignant glandular epithelial cells. "We evaluated NDRG2 SUMOylation in lung adenocarcinoma cells and its underlying molecular mechanism." (PMID 27072586, 2016). "Additionally, the progression of lung adenocarcinoma is thought to be influenced by the lncRNA C5orf64/miR-582-5p/NDRG2/TLR2 axis." (PMID 40580075, 2025). "In human lung adenocarcinomas cells, RNF4 targeted NDRG2 to proteasomal degradation by stimulating its SUMOylation." (PMID 27072586, 2016).
lymph node metastasis (4 papers, 2015 to 2020). "The data shows that loss of Ndrg2 protein significantly correlated with H. pylori (HP) infection (P=0.000), venous invasion (P=0.011), lymphatic involvement (P=0.003), invasive depth (P=0.000), lymph node metastasis (P=0.000), distant metastasis (P=0.000) and clinical stage (P=0.000)." (PMID 25823664, 2015). "Furthermore, low NDRG2 expression was related to some phenotypes of tumor aggressiveness, such as clinical stage (OR = 3.21, 95% CI: 1.96–5.26, P < .001), lymph node metastasis (OR = 2.14, 95% CI: 1.49–3.07, P < .001), and degree of differentiation (OR = 0.60, 95% CI: 0.45–0.81, P = .001)." (PMID 33031336, 2020). "It was proposed that, in clinical investigations, NDRG2 is positively correlated with survival rate and disease-free survival (DFS) probability, and negatively correlated with lymph node metastasis and TNM stage." (PMID 31121982, 2019).
oral squamous cell carcinoma (4 papers, 2015 to 2024). "Additionally, NDRG2 inhibits tumorigenesis of oral squamous cell carcinoma." (PMID 34951340, 2022). "We previously observed that the expression of NDRG2 was low in many types of solid cancers, including SAS (oral squamous cell carcinoma) and U2OS (osteosarcoma), and cell proliferation was significantly suppressed by silencing PRMT5 expression with the degradation of AKT and NEMO proteins." (PMID 38474089, 2024). "Hypoexpression of NDRG2 may also activate the NF-κB signaling pathway to induce EMT, thereby significantly increasing the quantity and size of oral squamous cell carcinomas (OSCCs) as well as the likelihood of invasion into the neck lymph nodes." (PMID 30413609, 2018).
Stroke (4 papers, 2013 to 2025). Sudden impairment of blood flow to a part of the brain due to occlusion or rupture of an artery to the brain. "In contrast, knockout of NDRG2 in mouse brains resulted in increased susceptibility to stroke-induced brain edema and astrocytic swelling via an imbalance in Na+ and water transfer, suggesting a role of NDRG2 in electrolyte homeostasis." (PMID 40378957, 2025). "Our findings bring insight to the roles of NDRG2 in ischemic-hypoxic injury and provide potential targets for future clinical therapies on stroke." (PMID 23451161, 2013). "However, the results of another report on the role of NDRG2 in stroke were contradictory to our conclusion." (PMID 31250377, 2020).
triple-negative breast carcinoma (4 papers, 2016 to 2023). An invasive breast carcinoma which is negative for expression of estrogen receptor (ER), progesterone receptor (PR), and human epidermal growth factor receptor 2 (HER2). "We found that the tumor suppressor NDRG2 is correlated with EHF gene expression in triple-negative breast cancer cells, that EHF overexpression results in reduced cell proliferation and that apoptosis is promoted by the chemotherapeutic reagent treatment of EHF-overexpressing cells." (PMID 37958443, 2023). "Finally, we confirmed from TCGA data that PD-L1 expression in basal and triple-negative breast cancer patients was negatively correlated with the expression of NDRG2." (PMID 34885221, 2021).
adult T-cell leukaemia (3 papers, 2015 to 2024). "Expression of NDRG2 is frequently downregulated in adult T-cell leukemia-lymphoma (ATLL), resulting in enhanced phosphorylation in C-tail of PTEN and enhanced activation of the PI3K–AKT pathway." (PMID 26284192, 2015).
Cerebral ischemia (3 papers, 2019 to 2022). Restriction of arterial blood supply to the brain associated with insufficient oxygenation to support the metabolic requirements of the tissue. "These mice are susceptible to cerebral ischemia and exhibit increased interstitial glutamate levels in the brain, suggesting that NDRG2 plays an essential role in controlling glutamate excitotoxicity." (PMID 31250377, 2020). "Here, we used the Ndrg2−/− mice to explore the underlying function of NDRG2 in cerebral ischemia and concluded that NDRG2 plays a neuroprotective role." (PMID 31250377, 2020). "This occurs even in the energy-restricted state of cerebral ischemia since the NDRG2 protein, once stabilized by lactate binding, remains quite stable." (PMID 36572898, 2022). "Here, we also found that the expression of NDRG2 increased after cerebral ischemia in vivo or glutamate stimulation in vitro." (PMID 31250377, 2020). "NDRG2 was reported as an early-stage stress-responsive gene, and its expression can be induced by several types of stimulation, including cerebral ischemia." (PMID 31250377, 2020). "In response to cerebral ischemia, excessive glutamate is released from the presynaptic membrane, and astroglial NDRG2 is rapidly upregulated." (PMID 31250377, 2020). "Collectively, these results indicate that astroglial NDRG2 plays a neuroprotective role in cerebral ischemia and is a potential therapeutic target in brain stroke." (PMID 31250377, 2020). "While NDRG2 is normally expressed at a moderate level in the brain, its expression was notably increased under excitotoxic conditions, including cerebral ischemia and trauma." (PMID 31250377, 2020). "Upregulation of NDRG2 was also seen in rat brain directly after cerebral ischemia, after which NDRG2 levels declined again." (PMID 31485792, 2019). "We therefore explored whether an NDRG2 treatment could improve neurological function after brain ischemia." (PMID 31250377, 2020). "Increasing or rescuing the expression of NDRG2 in WT and Ndrg2−/− mice significantly reduces the infarct volume, neurological outcome, and interstitial glutamate levels, suggesting a potentially therapeutic target for brain ischemia." (PMID 31250377, 2020). "NDRG2 may be a new therapeutic target for cerebral ischemia." (PMID 36572898, 2022). "After an initial increase of NDRG4, decreased levels of NDRG4 were observed, resembling the expression of NDRG2 and NDRG3 during cerebral ischemia." (PMID 31485792, 2019). "NDRG2, NDRG3, and NDRG4 also seem to be involved in brain ischemia." (PMID 31485792, 2019).
chronic lymphocytic leukemia (3 papers, 2018 to 2024). "While miR-23a and -23b have not been described elsewhere to target human or rodent Ndrg2, miR-28-5p was reported recently to target and suppress human NDRG2 in chronic lymphocytic leukemia cells." (PMID 31138100, 2019). "However, few studies have ever been done on the role of NDRG2 and the NDRG2-regulating miRNAs interference in chronic lymphocytic leukemia (CLL)." (PMID 30348117, 2018). "On the other hand, in chronic lymphocytic leukemia (CLL), CRNDE regulates the expression of NDRG2 through miR-28, where it suppresses the proliferation and stimulates apoptosis of MEG1 and HG3 cells." (PMID 39335585, 2024). "However, few data are available on the role of NDRG2 in chronic lymphocytic leukemia (CLL)." (PMID 30348117, 2018).
esophageal cancer (3 papers, 2018 to 2022). A primary or metastatic malignant neoplasm involving the esophagus. "Low NDRG2 expression is associated with pAKT and XIAP upregulation, while overexpression of NDRG2 suppresses AKT/XIAP signaling pathway and EMT in esophageal cancer cells." (PMID 36012631, 2022). "For instance, increased NDRG2 suppresses esophageal cancer cell proliferation, migration, invasion, and EMT." (PMID 34951340, 2022).
ischemic stroke (3 papers, 2020 to 2025). A stroke disorder caused by obstruction of blood flow to the brain, due to thrombotic (local blood clot formation) or embolic (due to a blood clot or other material traveling from another site) event. "In a mouse model of ischemic stroke, NDRG2 protein expression was markedly increased in the nucleus of astrocytes in ischemic penumbra at 24 h, while in the control, NDRG2 was predominantly localized in the cytoplasm." (PMID 40378957, 2025). "NDRG2 is required for astroglial glutamate uptake from cerebral interstitial fluid, as it interacts with Na+/K+-ATPase β1, which protects the brain from ischemic stroke." (PMID 31250377, 2020). "Hence, this study provides new insights into targeting NDRG2 as a potential therapeutic and neuroinflammatory strategy for ameliorating the adverse effects of ischemic stroke." (PMID 36572898, 2022). "Taken together, these results indicate that NDRG2 silencing may have a meaningful impact on neuroinflammatory reactions in the progression of ischemic stroke." (PMID 36572898, 2022). "A series of studies have suggested that NDRG2 played important roles in maintaining the integrity of the blood–brain barrier (BBB), alleviating brain edema, and inhibiting glutamate excitotoxicity after ischemic stroke." (PMID 36572898, 2022).
liver fibrosis (3 papers, 2011 to 2022). "And it inhibited the activation of HSCs by regulating TGFβ1/NDRG2/MAPK signaling axis in CCl4-induced liver fibrosis Our study newly found that NLPC0393 inhibited the differentiation of WB-F344 cells into cholangiocytes in a Gli1-dependent manner." (PMID 36483737, 2022). "Given that TGF-β1 is a crucial factor in the progression of liver fibrosis and has been reported to inhibit NDRG2 expression in HSCs, we validated the effects of NPLC0393 on TGF-β1-induced downregulation of NDRG2." (PMID 33329740, 2020). "In conclusion, these results provide information on the mechanism underlying the antifibrotic effect of NPLC0393 and shed new light on the potential therapeutic function of the TGF-β1/NDRG2/MAPK signaling axis in liver fibrosis." (PMID 33329740, 2020). "This study demonstrates that N-Myc downstream-regulated gene 2 (NDRG2) is a potential regulator of liver fibrosis as NDRG2 mRNA and protein levels were reduced during HSCs activation." (PMID 22110735, 2011). "Collectively, the data reported in this study have demonstrated, for the first time, that NDRG2 is involved in the regulation of liver fibrosis." (PMID 22110735, 2011). "In conclusion, the present findings indicate that the modulation of NDRG2 is a promising strategy for the treatment of liver fibrosis." (PMID 22110735, 2011). "Furthermore, adenovirus-mediated NDRG2 overexpression attenuated rat liver fibrosis and improved liver function by enhancing ECM degradation via the alteration of MMP2 and TIMP2 expression." (PMID 22110735, 2011). "However, to date, the significance of NDRG2 in the development of liver fibrosis has been little studied." (PMID 22110735, 2011). "The discrepancies between these two studies may be attributed to the complexity of the NDRG2 regulation network in different liver tissue remodeling microenvironments (PH-induced liver regeneration compared to DMN-induced liver fibrosis)." (PMID 22110735, 2011). "Thus, a single dose of adenovirus was enough to enhance NDRG2 expression, which lasted long enough to produce a therapeutic effect on liver fibrosis." (PMID 22110735, 2011). "Thus, it is conceivable that modulating NDRG2 expression may provide a novel therapy for intervention in liver fibrosis." (PMID 22110735, 2011). "Furthermore, the in vivo study indicated that adenovirus-mediated NDRG2 treatment could effectively attenuate liver fibrosis and improve liver function." (PMID 22110735, 2011). "Consequently, NDRG2 administration reduced ECM deposition within the liver parenchyma and alleviated liver fibrosis." (PMID 22110735, 2011). "Our results provide insight into the profibrotic mechanism of non-canonical TGF-β1 signaling pathway and suggest that NDRG2 could be a therapeutic target for liver fibrosis." (PMID 33329740, 2020).